CD24 (CD24 molecule)
Diseases named in the same sentence as CD24 in open-access papers (continued):
Sharing a sentence is not in itself a finding about the gene and the disease.
ovarian carcinoma (continued). "These biological behaviours of CDC50A+ ovarian cancer cells were consistent with those of ovarian cancer cells with positive expression of several classic stem cell surface biomarkers, such as CD44, CD117, CD24 and CD133." (PMID 35982417, 2022). "Besides, CD24 and EGFR have also been characterized in exosomes derived from ovarian cancer patients and proposed to be potential biomarkers for ovarian cancer." (PMID 36109501, 2022). "Pre-clinically, neutralising anti-CD47 and anti-CD24 mAbs have demonstrated enhancement of non-specific macrophage phagocytosis of ovarian cancer cells in vitro, as well as inhibition of tumour growth in murine ovarian cancer models." (PMID 35020853, 2022). "Although current evidences show that various biological markers could predict the prognosis of ovarian cancer, such as CA125, HE4, CD24, CD44, CD133, SSEA and so on, few targets reported are related to tumor metabolism." (PMID 33403023, 2021). "A previous study identified CD24, CD44, CD117, CD133, and ROR1 as ovarian cancer stem cells." (PMID 32035490, 2020). "The aim of this review is to present the clinical and preclinically evaluated biomarkers for ovarian cancer FIGS, highlight the strengths of CD24, and propose a future bimodal approach combining CD24-targeted fluorescence imaging with radionuclide detection and targeted therapy." (PMID 33260974, 2020). "Once the presence of EpCAM positive CTCs in the blood of patients was confirmed using two methodologies, an expression profile analysis, including a panel of genes related to cell plasticity and ovarian cancer aggressiveness (MUC1, CK19, CXCR4, TIMP1, ALDH1, CD24, CD44, GDF1), was carried out." (PMID 32423054, 2020). "This device was functionalized with CD63 or CD24 to capture EVs from ovarian cancer patient ascites (n=20) and noncancer patients (n=10)." (PMID 31212643, 2019). "Furthermore, platinum-resistant ovarian cancer cells showed a higher expression of several cancer stem cell markers, such as ALDH1, CD24, and EpCAM, which are known direct targets of Wnt/β-catenin signaling." (PMID 31261739, 2019). "Surprisingly, despite a high rate of CD24 amplification in ovarian cancer, such amplification has no prognostic value for OS rate." (PMID 31244889, 2019). "Thus, E-Cadherin, P-Cadherin, Zeb1, HMGA2, Rab25, CD24, NCAM (CD56), Sox11 and Vimentin expression was assessed in 100 advanced-stage ovarian cancer patients undergoing platinum-based chemotherapy." (PMID 29389895, 2018). "Cytoplasmic staining for CD24 protein was absent in normal epithelium in ovarian cancer, and present in ovarian adenocarcinoma, and its overexpression was independently linked to a worse survival." (PMID 26394139, 2015). "Similarly, a CD24+/CD44+ cancer stem cell subpopulation has been identified in solid tumors and cancer cell lines in both colorectal and ovarian cancers." (PMID 24612587, 2014). "Examples of EVs-related proteins in the context of ovarian cancer tumor biomarker detection include CD9, MUC1 (detected by aptamer-conjugated spiky Au@Fe3O4), and simultaneous detection of various markers like CD63, EpCAM, CD24, and CA-125 to avoid false positives." (PMID 40277517, 2025). "However, the relation between CD24 and miRNA expression and its roles in CSC phenotype acquisition in ovarian cancer remains unknown." (PMID 38360723, 2024). "Similarly, other studies also reported that in the CD24 level in metastatic ovarian carcinomas are higher than ovarian carcinomas without metastases." (PMID 37359556, 2023). "CD44+/CD24–/low cells have been described as breast and prostate cancer stem cells; stem-like properties, including increased proliferation, angiogenesis, and resistance to chemotherapy, have been attributed to CD44+/CD24–/low NSCLC, and ovarian cancer cells as well." (PMID 36013184, 2022).
ovarian carcinoma (continued). "A number of markers expressed on ovarian cancer stem cells have been described in the literature: CD133 (prominin), ALDH (aldehyde dehydrogenase), CD44 (hyaluronan), CD117 (c-kit), MyD88 (myeloid differentiation primary response protein), CD24 (mucin-like adhesion molecule)." (PMID 34440558, 2021). "Administration with CD24-shRNA in vivo suppressed tumor volume increase by microvessel density (MVD) decrease, cell proliferation inhibition, and apoptosis induction, suggesting that knockdown of CD24 may be a potential method for the treatment of human ovarian cancer." (PMID 32765491, 2020). "Cancer cells overexpressing CXCR4 and CD133 were evaluated in fresh primary human ovarian cancer revealing extremely variable levels of CXCR4+/CD133+ and CD24+/CD44+ positive cells, without significant differences among the group of patients." (PMID 26020117, 2015). "Tumors lacking CD24 expression have been found to be more sensitive to CD47 blockers, suggesting that simultaneous targeting of CD24 and CD47 may offer better clinical prospects for treating ovarian cancer." (PMID 39003350, 2024).
pancreatic cancer (160 papers, 2008 to 2026). "The extract also inhibited CD44+/CD24+/EpCAMhigh pancreatic cancer stem cell (CSC) populations, CSC-associated markers SOX2, OCT4, NANOG and CD44 in-vitro and in-vivo, and increased sensitivity to gemcitabine." (PMID 32726914, 2020). "Pancreatic tumours with impaired expression of Six1 showed significantly delayed growth and displayed loss of the CD24+/CD44+ phenotype." (PMID 28388884, 2017). "Another report showed CD24 mRNA was upregulated in the pancreatic cancer cell line S2-013 where CD24 gene was considered metastasis-associated." (PMID 27332878, 2016). "In addition, CD24 expression and its prognostic significance have been reported for many types of cancer including breast, colorectal, gastric, lung, ovarian and pancreatic cancers, supporting CD24 as a diagnostic marker of cancer." (PMID 27955675, 2016). "In addition to NPC cells, CD24 is associated with CSCs of other tumors, such as ovarian and pancreatic cancer." (PMID 24955581, 2014). "CD24 has been proposed to be a marker of pancreatic cancer stem cells and may be associated with unfavorable prognosis." (PMID 21714887, 2011). "Specific polymorphisms in the APC and CD24 genes may play a role in pancreatic cancer development." (PMID 26394139, 2015). "In pancreatic cancer, knockdown of cytoplasmic CD24 enhances tumor progression by increasing invasiveness and liver metastasis." (PMID 39136818, 2025). "An increased proportion of CD24+ cells has been identified within the context of gemcitabine-resistant pancreatic cancer cells." (PMID 40486886, 2025). "Experiments have shown that radiotherapy-resistant pancreatic cancer cells express higher levels of CD24 and have stronger tumorigenicity both in vitro and in vivo." (PMID 40486886, 2025). "A study on pancreatic cancer stem cells with high expression of CD24 has shown that EMT mediates the resistance of cancer cells to gemcitabine." (PMID 40486886, 2025). "In pancreatic cancer, the resistance of tumors to radiotherapy is closely related to the presence of apoptosis-resistant CSCs, and CD24 is also one of the biomarkers of pancreatic cancer stem cells." (PMID 40486886, 2025). "For PANC-1, we assessed CD24, CD44, and EpCam since these have been linked with a more specific phenotype for CSCs in pancreas cancer." (PMID 38542325, 2024). "FH535 has also demonstrated anti-CSC activity in pancreatic cancer models, reducing clonogenicity and CD24−/CD44+ marker expression in vitro, as well as inhibiting metastasis and tumor growth in xenograft models." (PMID 38612911, 2024). "ADP-ribosylation of the RNA helicase DDX5 by poly (ADP-ribose) polymerase 1 (PARP1) controls CD24 transcription in pancreatic cancer, according to research." (PMID 38279998, 2024). "Here, we discovered that silencing CDK1 significantly inhibited a subgroup of CD44+/CD24+ cells as well as the tumor stemness of pancreatic cancer." (PMID 37743465, 2023). "Consistently, high DDX5 expression in pancreatic cancer tissues was correlated to high CD24 expression, while the PARylation activity of PARP1 was inversely correlated with CD24 expression." (PMID 37596619, 2023). "Correlations between the antiproliferative effect and CD24 expression levels were observed and dual CD24 inhibition with SWA11 and ML-5 prevented the spread of CD24+ pancreatic cancer cell lines." (PMID 37846296, 2023). "Because aldehyde dehydrogenase 1 (ALDH1), CD44 and CD24 are well recognized cell surface markers for the stemness of pancreatic cancer cells, we next used these molecules as indicators to examine cell stemness." (PMID 37280198, 2023). "Anti-CD24 CAR-T appears to be the first to make good progress in the treatment of pancreatic cancer." (PMID 38137380, 2023). "An experiment demonstrated that obstructing CD24 with a monoclonal antibody improved macrophages’ ability to phagocytose pancreatic cancer cells (Capan-1 and Panc-1)." (PMID 38137380, 2023).
pancreatic cancer (continued). "CD133+/CD44+/CD24+/ESA+ PCSCs isolated from human primary pancreatic tumor were orthotopically injected into NOD/SCID/IL2R gamma mice." (PMID 36776295, 2023). "A subpopulation of pancreatic cancer cells showing CD44+CD24+ESA+ have been proven to possess stem cell-like properties of self-renewal and the ability to produce differentiated progeny." (PMID 37108495, 2023). "Pancreatic CSCs (PCSCs), that represent approximately 0.5-1% of pancreatic cancer cells, are characterized by the expression of the surface markers CD44+/CD24+, CD133+ and ESA+, and their presence is associated with poor prognosis." (PMID 36776295, 2023). "As a matter of fact, CD44+/CD24+ pancreatic cancer cells that express epithelial-specific antigens appear to possess several stem-like properties that have led them to be considered as tumor-initiating cells." (PMID 36013184, 2022). "CD44(+)/CD24(+) fractions from pancreatic tumors are enriched in sphere-forming cells, and nestin, which is a CSC marker of PDAC, had increased expression in the spheres of the three PDAC cell lines than in the non-sphere cells." (PMID 35629168, 2022). "SWA11, which is another monoclonal antibody against CD24, reduced proliferation in human lung, ovarian, and pancreatic cancer cell lines and impeded tumor growth in human colorectal cancer xenograft models." (PMID 36013184, 2022). "In pancreatic cancer cells, quercetin can inhibit the expression of pancreatic cancer stem cell surface markers CD24 and CD133, and also induce its differentiation through β-cyclonectin." (PMID 36686745, 2022). "First of all, we systematically evaluated the two putative pancreatic cancer stem cells phenotypes ESA+CD24+CD44+ and CXCR4+CD133+ in all cell lines." (PMID 36142575, 2022). "Shah and colleagues from M.D. Anderson showed that pancreatic cancer cell lines that selectively grew in culture media containing therapeutic doses of gemcitabine increased in expression of the stem cell markers CD24, CD44, and ESA." (PMID 36142575, 2022). "For example, pancreatic cancer cells possessing high CD24 expression were determined to induce tumor initiation, while low levels of CD24 expression were observed in breast CSCs." (PMID 35395804, 2022). "We isolated cancer stem cells (CSCs) from the human PANC-1 pancreatic cancer cell line as CD44+CD24+EpCAM+ cells." (PMID 34885233, 2021). "Leptin overexpression promotes human pancreatic cancer xenograft growth and lymph node metastasis in mice, inducing the progression throughout the cell cycle and the expression of pancreatic cancer stem cell (CSC) markers (CD24+, CD44+, ESA+, ALDH+)." (PMID 33670492, 2021). "Cell populations expressing CD24 are identified as cancer stem cells (CSCs) in ovarian and colorectal cancer, nasopharyngeal carcinoma and pancreatic cancer cells." (PMID 34360932, 2021). "CD44+ CD24+ epithelialspecific antigen pancreatic cancer cells demonstrated stem cell properties such as self-renewal, tumorigenic capacity, maintenance of tumor growth, and resistance to chemo- or radiation therapy." (PMID 34094034, 2021). "Cytoplasmic CD24 was shown to inhibit pancreatic cancer cell invasion by post-transcriptional regulation of BART through interaction with G3BP." (PMID 34360932, 2021). "Numerous molecular markers, including Cd24, Cd44, Prom1 (Cd133), and other genes, have been applied in order to define pancreatic cancer stem cells (CSCs)." (PMID 32429174, 2020). "In a previous report, pancreatic cancer cells expressing CD24/CD44 or CD133 functioned as CSCs and exhibited tumorigenesis and chemoresistance." (PMID 32266133, 2020). "CD24 is expressed in lung, kidney, ovarian, and pancreatic cancers, and is considered a potent CSC marker whose overexpression indicates lymph node metastasis and poor prognosis." (PMID 30467381, 2019). "CD24 cell membrane and intracellular expression in pancreas cancer inhibits the cancer cell invasion and metastasis." (PMID 31579438, 2019).
pancreatic cancer (continued). "Our results revealed that low-dose gemcitabine treatment (1–5 μM) for 24 h, which has a minimal killing effect on pancreatic cancer cells, induced the expression of stemness-associated molecules Bmi1 and Sox2 as well as the CSC marker CD24." (PMID 30486896, 2018). "In this study, the Patu8988 pancreatic cancer cells were given 2.5 μg/mL gemcitabine treatment for 48 h, then pancreatic CSCs markers CD24 and CD133, were detected by flow cytometry." (PMID 29018223, 2017). "We found that 2‐DG effectively decreased the expression of the pancreatic cancer stemness markers CD24 and CD133 and reduced the levels of pluripotency markers Nanog and Sox2 in both protein and mRNA levels." (PMID 28244691, 2017). "Various studies have reported that CD24 expression was highly correlated with the progression of pancreatic cancer." (PMID 28369074, 2017). "As CD44+CD24+ESA+ or CD133+ pancreatic cancer cells exhibited stem cell properties, flow cytometry demonstrated the presence of a rare CSCs population." (PMID 29254186, 2017). "Recent studies have identified that the positive selection of CD24 selects for cancer stem cells in several cancers, including pancreatic cancer colorectal cancer, liver, and ovarian cancer." (PMID 27276062, 2016). "Intriguingly, a large volume of evidence has shown that CD24+ tumor cells are TPCs for pancreatic cancer, Cholangiocarcinoma and colon cancer." (PMID 27276062, 2016). "CD24+/CD44+ pancreatic cancer cells have a significantly higher possibility for forming colonies in vitro and are more resistant to irradiation." (PMID 27323403, 2016). "Further, we show that activation of the WNT pathway stabilizes intracellular CD24 protein in pancreatic tumor cells, and that inhibition of GSK3β has the same effect, while transcriptional activation of β-catenin is not required in this process." (PMID 27203385, 2016). "Pancreatic cancer cells expressing the cell surface marker CD44+ CD24+ ESA+ phenotype had a 100-fold increased tumorigenic potential compared to non-tumorigenic cancer cells." (PMID 27649156, 2016). "Markers for prospectively identifying pancreatic cancer stem cells are CD44+CD24+EpCAM+, CD133+, and ALDH+." (PMID 26673007, 2016). "In particular, it was reported that CD24 expression in intracellular vesicles inhibits cell invasion in pancreatic cancer cells." (PMID 27203385, 2016). "Presently, we discovered that FH535 decreased the population of CD24+/CD44+ pancreatic cancer cells, the presumed pancreatic CSCs." (PMID 27323403, 2016). "Li and colleagues firstly identified that CD44+/CD24+/ESA+ pancreatic cancer cells showed the stem cell properties, including self-renewal, multi-differentiation and tumorigenicity." (PMID 26840020, 2016). "An intracellular study on pancreatic cancer indicated CD24 expression both in membrane and cytoplasm impeded cell invasion and metastasis." (PMID 27332878, 2016). "In the pancreatic cancer cells L3.6pl contained 59.1% CD24+/CD44+ cells of which 94.9% were EpCAM+/CD166+, yielding a 56.1% CSC subset." (PMID 27512958, 2016). "High expression of CD24 leads to progression of lung, prostrate, colon, and pancreatic cancers, among others." (PMID 26301220, 2015). "The current study sought an association between four different CD24 SNPs, two APC genetic variants, and the clinical course of pancreatic cancer." (PMID 26394139, 2015). "Firstly, several studies have reported CD24 expression in various other malignant conditions, including B-cell lymphomas, gliomas, lung, breast, urothelial tumors, and pancreatic cancer." (PMID 26078485, 2015). "Previous studies have shown that CD24 is a marker for a variety of cancer stem cells, including pancreatic cancer." (PMID 26394139, 2015). "CD24 is often used to identify and enrich cancer stem cells (CSCs) in cancers such as ovarian and pancreatic cancer." (PMID 26311117, 2015).